PFKFB4 (6-phosphofructo-2-kinase/fructose-2,6-biphosphatase 4)
Diseases named in the same sentence as PFKFB4 in open-access papers (continued):
Sharing a sentence is not in itself a finding about the gene and the disease.
prostate carcinoma (19 papers, 2013 to 2023). A carcinoma that arises from epithelial cells of the prostate gland. "PFKFB4 has also been implicated in cell survival in prostate cancer by regulating antioxidant production through the pentose phosphate pathway (PPP), and PFKFB4 has also been shown to be associated with PPP activity in clear-cell renal cell carcinoma." (PMID 36115843, 2022). "In PC3 prostate cancer cells, PFKFB4 inhibition was observed to cause p62 accumulation, which is usually associated with the inhibition of autophagy." (PMID 30234009, 2018). "Previous reports have indicated that elevated PFKFB4 expression levels occur in various types of cancer (e.g., prostate cancer, bladder cancer, gastric cancer) 23-27." (PMID 34976184, 2022). "PFKFB4 is required to maintain the balance of glycolytic activity for energy generation and cellular redox in prostate cancer." (PMID 31244553, 2019). "PFKFB4 silencing selectively increases Fru-2,6-P2 concentration in prostate cancer cells, suggesting that it mainly functions as a fructose-2,6-bisphosphatase in these particular cells." (PMID 30234009, 2018). "PFKFB4 is required to balance glycolytic activity and antioxidant production to maintain the cellular redox balance in prostate cancer cells." (PMID 30234009, 2018). "PFKFB4 mRNA expression has been found to be greater in metastatic prostate cancer cells than in primary tumors." (PMID 30234009, 2018). "In this study, we found that PDK1 and PFKFB4 played a role in regulating the proliferation, invasion and migration of prostate cancer cells." (PMID 29029419, 2017). "First, we investigated the effects of PDK1 and PFKFB4 for prostate cancer cell proliferation using MTT assay." (PMID 29029419, 2017). "In this study, shRNA-mediated PDK1 and PFKFB4 ablation in prostate cancer cells should alleviates the aggressive such as cell proliferation, cell migration and invasion." (PMID 29029419, 2017). "For example, silencing of 6-Phosphofructo-2-Kinase/Fructose-2,6-Biphosphatase 4 (PFKFB4), a protein responsible for regulating carbon entering glycolysis, only induced apoptosis in prostate cancer lines derived from metastasis when grown in low serum." (PMID 28060271, 2016). "Most published results have reported that the PFKFB gene over-expressed in cancer is PFKFB3, although, as noted, a recent result was cited that indicated over-expression of PFKFB4 in three different prostate cancer cell lines." (PMID 25859558, 2015). "Knockdown of PFKFB4 blocked prostate cancer cell growth and remarkably induced regression of prostate tumor xenografts, confirming that prostate cancer cells are dependent on PFKFB4 for survival." (PMID 24280138, 2013). "PFKFB4 is involved in androgen-independent growth in human prostate cancer tissues." (PMID 37919747, 2023). "PFKFB4 mediates CD44-driven proliferation in prostate cancer cells." (PMID 37919747, 2023). "In prostate cancer cells, PFKFB4 balanced glycolysis and antioxidant production." (PMID 35917405, 2022). "Similarly, enhanced glycolysis during the androgen-independent growth of LNCaP-AI cell line and tumor progression were verified attributed to PFKFB4 overexpression in prostate cancer." (PMID 34593007, 2021). "Taken together, high expression of PFKFB4 was the hallmark of tumor proliferation and androgen-independent growth, which suggested PFKFB4 might be a novel biomarker in prostate cancer." (PMID 32487245, 2020). "Thus, CD44 can modulate the aggressive phenotype of prostate cancer cells by increasing PFKFB4 expression." (PMID 30234009, 2018). "Silencing of PDK1 and PFKFB4 could decrease cell proliferation, inhibit invasion and migration ability of prostate cancer cells." (PMID 29029419, 2017). "We found the prostate cancer cells which transfected with PDK1 or PFKFB4 shRNA obtained slower closure of the scratched wound, and the relative cell migration of LNCaP and PC3 cells were decreased significantly compared with the cells infected negative vector control cells and blank cells." (PMID 29029419, 2017).
prostate carcinoma (continued). "However, a third study found that PFKFB4 siRNA increased the F2,6BP concentration of three prostate cancer cell lines including the LNCaP and PC3 cell lines (using one of the two siRNAs examined in the current study)." (PMID 25115398, 2014). "Silencing of PFKFB4 resulted in increased levels of Fru-2,6-P2 in prostate cancer cells." (PMID 24280138, 2013). "Interestingly, PFKFB4 silencing has also been demonstrated to be detrimental for prostate cancer cell survival." (PMID 24280138, 2013). "Moreover, the requirement of PFKFB4 for cell survival seems to be extended beyond prostate cancer because other cancer cell lines were also sensitive to PFKFB4 knockdown." (PMID 24280138, 2013). "Prostate cancer cells may then selectively rely on PFKFB4 for managing ROS accumulation, since treatment with a ROS scavenger rescued the viability defect in the PFKFB4-knockdown prostate cancer cells." (PMID 24280138, 2013). "Notably, PFKFB4 was not only required for the survival of prostate cancer cells, but also for other cancer cell lines from different tissues." (PMID 24280138, 2013). "This would explain why prostate cancer cells show lower NADPH and glutathione levels after PFKFB4 silencing, which results in enhanced oxidative stress and cell death." (PMID 30234009, 2018). "Taken together, it was possible that CD44 regulates prostate cancer proliferation, invasion and migration via PDK1 and PFKFB4." (PMID 29029419, 2017). "Taken together, CD44 could modulate aggressive phenotype of prostate cancer cells, by regulation of the expression of PDK1 and PFKFB4." (PMID 29029419, 2017).
glioma (16 papers, 2014 to 2025). A benign or malignant brain and spinal cord tumor that arises from glial cells (astrocytes, oligodendrocytes, ependymal cells). "On the other hand, PFKFB4 plays an essential role in the survival of glioma stem-like cells and loss of PFKFB4 induced apoptosis in these cells." (PMID 24383451, 2014). "For instance, PTBP1 lactylation was found to facilitate glioma stem cell maintenance through PFKFB4-driven glycolysis." (PMID 41035644, 2025). "Of particular relevance to glioblastoma is the finding that PFKFB3:PFKFB4 mRNA ratios are of prognostic value to high grade glioma, with increasing PFKFB4 levels correlating unfavorably with patient survival." (PMID 36115843, 2022). "PI3K-AKT signaling has documented an important HCC-promoting pathway, and a recent study has shown that transcriptional enhancement of the PFKFB4 expression promotes glioma malignancy progression by activating PI3K/AKT signaling." (PMID 34970545, 2021). "Consistently, it has been documented that PFKFB4 exerts its oncogenic effect on glioma via increased activation of PI3K/AKT signaling." (PMID 34970545, 2021). "Our analysis revealed that in the case of Glioma and Liver hepatocellular carcinoma patients with high PFKFB4 expression have significantly lower overall survival rates in comparison to patients with low expression of PFKFB4." (PMID 31754349, 2019). "Modulating the glioma chemoresistant phenotype by inhibiting PFKFB4 and HMOX1 may enhance TMZ or DOX therapy." (PMID 40739397, 2025). "In glioma cells, PTBP1 stabilizes PFKFB4 mRNA to promote glycolysis, whereas in gastric cancer cells, it accelerates the degradation of TXNIP mRNA to alleviate oxidative stress.​​." (PMID 41313521, 2025). "We discovered that PFKFB4 and HMOX1 control glioma’s growth, migration, invasion, and malignancy by studying apoptotic genes and others." (PMID 40739397, 2025). "Genes involved in glycolysis, namely PKM2 and 6-phosphofructo-2-kinase/fructose-2,6-biphosphatase 4 (PFKFB4), were also identified as stemness regulators in glioma SCs." (PMID 29991569, 2018). "Importantly, our analysis confirmed the previously published negative impact of PFKFB4 on the prognosis of glioma patients and negative impact of PFKFB3 on the prognosis of hepatocellular cancer." (PMID 31754349, 2019).
glioblastoma (15 papers, 2018 to 2025). The most malignant astrocytic tumor (WHO grade IV). "PFKFB4 was shown to be associated with a poor prognosis in many cancers, such as glioblastoma and bladder cancer." (PMID 36873244, 2023). "Knockdown of PFKFB4 triggered apoptosis of CSCs but overexpression of PFKFB4 was associated with a shorter survival of patients with glioblastoma." (PMID 34359941, 2021). "Moreover, PFKFB4 has been associated with cell survival in brain cancer stem cells derived from glioblastoma patients: PFKFB4 silencing suppresses viability and inhibits the production of ATP and lactate." (PMID 38139462, 2023). "Future research should investigate how knocking down HMOX1 and PFKFB4 affects drug resistance pathways in glioblastoma, such as PI3K/AKT, MAPK, and NF-κB." (PMID 40739397, 2025). "We also investigated the role of PFKFB4 and HMOX1 in glioblastoma growth by examining death-associated genes in U87-MG cells." (PMID 40739397, 2025). "Long-term studies are needed to assess the chronic efficacy and safety of targeting HMOX1 and PFKFB4 in glioblastoma models." (PMID 40739397, 2025). "Under normoxic conditions, glioblastoma cells exhibited higher levels of PFKFB4 and HMOX1 compared to normal fibroblast cells (HDFa)." (PMID 40739397, 2025). "This study aimed to enhance the cytotoxicity of DOX and TMZ against glioblastoma cells by targeting PFKFB4 and HMOX132." (PMID 40739397, 2025). "The metabolic enzyme 6-Phosphofructo-2-Kinase/Fructose-2,6-Biphosphatase 4 (PFKFB4) is essential for glioblastoma stem-like cell (GSC) survival but its mode of action is unclear." (PMID 36115843, 2022). "In order to investigate the importance of PFKFB4 for glioblastoma growth in vivo we used an orthotopic xenograft mouse model." (PMID 36115843, 2022). "Expression analysis of the Elvidge HIF-1α and HIF-2α signature in a cohort of glioblastoma patients (n = 152), available from The Cancer Genome Atlas (TCGA), revealed a positive correlation between PFKFB4 expression (r = 0.657) and HIF signaling." (PMID 36115843, 2022). "Here, we show the importance of PFKFB4 for glioblastoma growth in vivo in an orthotopic patient derived mouse model." (PMID 36115843, 2022). "A low PFKFB3:PFKFB4 mRNA ratio (7.7:1) has been found to be a poor prognostic factor in patients with IDH-wildtype primary glioblastoma." (PMID 34831136, 2021). "High PFKFB4 mRNA and protein expression have been described in three different glioblastoma stem-like cell lines, with shRNA-mediated knockdown of PFKFB4 promoting apoptosis and no phenotypic effect occurring in PFKFB4-silenced normal neural stem cells." (PMID 30234009, 2018). "Also, our data show that reduced PFKFB4 levels in U87-MG glioblastoma cells enhance the anti-angiogenic effect of DOX and TMZ." (PMID 40739397, 2025). "In conclusion, we found that PFKFB4 silencing decreased In vitro U87-MG glioblastoma cell growth." (PMID 40739397, 2025). "In addition, PFKFB4 blockage potentiates DOX-induced glioblastoma cytotoxicity with low toxicity on normal cells." (PMID 40739397, 2025). "Furthermore, PFKFB3 and PFKFB4 isoforms were considered markers of bad prognosis in patients with IDH-wild type glioblastoma." (PMID 38139462, 2023). "Moreover, PFKFB4 expression is an unfavorable prognostic marker in glioblastoma, as it inversely correlates with survival." (PMID 35565433, 2022). "In a previous study, we have shown that PFKFB4 is upregulated in GSCs compared to normal brain, and that its silencing leads to apoptotic cell death in GSCs, highlighting its potential as a therapeutic target in glioblastoma." (PMID 36115843, 2022). "Interestingly, high PFKFB4 expression is correlated with improved survival in glioblastoma and neuroblastoma patients." (PMID 34831136, 2021).
glioblastoma (continued). "This study investigated the potential of silencing the PFKFB4 and HMOX1 genes in U87-MG glioblastoma cells using small interfering RNAs (siRNAs), both alone and alongside the chemotherapeutic agents temozolomide (TMZ) and doxorubicin (DOX)." (PMID 40739397, 2025). "We primarily investigated the additive anti-proliferative and anti-migratory effects of HMOX1 and PFKFB4 knockdown alone or in combination with temozolomide (TMZ) and doxorubicin in U87-MG Glioblastoma Cells." (PMID 40739397, 2025). "The analysis revealed a significant upregulation of PFKFB4 and HMOX1 expression in the glioblastoma cells compared to the normal cells." (PMID 40739397, 2025). "The mRNA expression levels of the PFKFB4 and HMOX1 genes were assessed in both U-87 MG glioblastoma and HDFa normal cell lines using RT-qPCR." (PMID 40739397, 2025). "For example, one study showed that 6-phosphofructo-2-kinase/fructose-2, 6-biphosphatase 4 (PFKFB4) binds to FBXO28 to regulate the ubiquitination and proteasomal degradation of HIF-1α, promoting HIF-1α signaling in glioblastoma." (PMID 38267923, 2024). "In summary, this shows that PFKFB4 plays a critical role in glioblastoma, its silencing not only slowing tumor growth but resulting in an almost complete eradication of the tumor in this xenograft model." (PMID 36115843, 2022). "This correlation supports PFKFB4 being a relevant therapeutic target, not just in glioblastoma, but also in a range of other cancers." (PMID 36115843, 2022). "In glioblastoma stem cells, hypoxia-inducible factor (HIF)-1α, HIF-2α, GLUT3 and glycolysis-related enzymes, such as pyruvate dehydrogenase kinase (PDK) 1, PFKFB4, and PKM2, were upregulated and the stemness properties of CSCs enhanced." (PMID 34359941, 2021).
melanoma (13 papers, 2020 to 2024). A malignant, usually aggressive tumor composed of atypical, neoplastic melanocytes. "This assay thus showed that PFKFB4 depletion phenocopied ICMT loss for RAS addressing to the plasma membrane in melanoma cells." (PMID 35914811, 2022). "As a whole, this series of results showed that ICMT depletion phenocopied loss of PFKFB4, and that the two protein partners were likely acting in the same pathway impacting melanoma cell migration." (PMID 35914811, 2022). "We have previously linked elevated expression of PFKFB4 with embryonic cell migration in vivo, but in melanoma, whereas PFKFB4 has been linked to promoting the Warburg effect, its role in cell migration remains to be explored." (PMID 35914811, 2022). "A β-Elemene isopropanolamine derivative reduces the expression of 6-phosphofructo-2-kinase/fructose-2,6-bisphosphatase 4 (PFKFB4), a key enzyme in glycolysis, thus inhibiting glycolysis and triggering autophagy in melanoma cells." (PMID 39584140, 2024). "In sum, all these results suggested that PFKFB4 direct protein–protein interactions with ICMT impacted ICMT–RAS complex formation in melanoma." (PMID 35914811, 2022). "Using a survey of human melanoma cell lines transcriptomes, we have selected cells with high PFKFB4 levels, and explored PFKFB4 function in the biology of those cells, focusing on their migration in vitro." (PMID 35914811, 2022). "To understand if PFKFB4 controlled melanoma cells migration using either its kinase or its phosphatase enzymatic activities, we compared the rescue phenotype of PFKFB4 depletion by various X. laevis PFKFB4 mutants." (PMID 35914811, 2022). "Our results demonstrated that β-elemene isopropanolamine derivative LXX-8250 induced apoptosis by inhibiting autophagic flux and glycolysis via suppression of PFKFB4 expression in melanoma cells." (PMID 36034839, 2022). "Together, these observations suggested that PFKFB4 levels significantly affect the average speed of melanoma cells migration, independently of the rate of glycolysis." (PMID 35914811, 2022). "Here we reported that shPFKFB4 transfection reduced the production of lactic acid and F-1,6-BP while PFKFB4 overexpression increased the production of lactic acid and F-1,6-BP in melanoma cells." (PMID 36034839, 2022). "LXX-8250 treatment inhibited the growth of melanoma xenografts and suppressed PFKFB4 expression and glycolysis in vivo." (PMID 36034839, 2022). "Analysis of TCGA and GTEx data showed that PFKFB4 was significantly upregulated in melanoma compared with those in normal tissue." (PMID 36034839, 2022). "The frog PFKFB4 expression plasmid was efficiently translated in human melanoma cells and recognized by the antibody designed against human PFKFB4." (PMID 35914811, 2022). "Altogether these results suggest that PFKFB4 regulated the efficiency of melanoma cell migration independently of variations in glycolysis, cell survival rate or cell cycle." (PMID 35914811, 2022). "Collectively these data suggest that LXX-8250 treatment inhibits the growth of melanoma in vivo via repressing PFKFB4 expression and glycolysis." (PMID 36034839, 2022). "Recent studies have demonstrated that the high expression of PFKFB4 predicts a poor prognosis in various types of cancer, including breast, gastric; lung; melanoma; and thyroid cancer." (PMID 36497200, 2022). "Taken together, LXX-8250 treatment induced apoptosis through inhibiting autophagic flux and glycolysis in melanoma cells, which was mediated by suppression of PFKFB4 expression." (PMID 36034839, 2022). "Here, human melanoma cells present similar regulations by PFKFB4, implicating AKT signaling and the control of cell migration." (PMID 35914811, 2022). "Our research has shown that five isoforms of PFKFB4 are expressed in melanoma cells, of which the D and F isoforms are highly constitutive, while the canonical B isoform seems to be the main isoform induced in hypoxia." (PMID 34445551, 2021).